LETM1 (leucine zipper and EF-hand containing transmembrane protein 1)
Diseases named in the same sentence as LETM1 in open-access papers (continued):
Sharing a sentence is not in itself a finding about the gene and the disease.
cancer (continued). "With more studies, we were gratified to find that knockdown of LETM1 significantly reduced ESCC cell proliferation, invasion and migration, which was consistent with the role of LETM1 in other cancers." (PMID 34605738, 2021). "As an exciting result, the overexpression of KIF14 significantly reversed the inhibited effect on cancer cells induced by LETM1 silence." (PMID 34605738, 2021). "According to the catalogue of somatic mutations in cancer (COSMIC) database, there have been 183 somatic mutations in LETM1 associated with breast, liver, kidney, lung, prostate, hematopoietic and lymphoid tissue cancers." (PMID 30642051, 2019). "To evaluate the interaction between LETM1 expression and the stem cell like characteristics of LETM1 positive cells, we analyzed and compared its expression with that of other cancer stemness-related genes such as CD44, LSD1, Sox2 and Sox9." (PMID 31500591, 2019). "In order to determine if LETM1 expression is associated with the cancer stemness in NSCLC, we investigated the correlation between LETM1 and cancer stemness related genes expression in NSCLC." (PMID 31500591, 2019). "Thus, future studies should concentrate on the relationship between cancer progression and LETM1, to gain new insight into novel strategies for cancer therapy and/or diagnosis." (PMID 35680871, 2022). "This hypothesis provides a possible mechanism by which the increased expression of LETM1 in cancer cells may be utilized as a means for delivering therapy." (PMID 33815143, 2021). "LETM1-mediated regulation of mitochondrial biogenesis, metabolism, and cell survival signaling has provided impetus to investigate LETM1 activity in various human cancers." (PMID 33815143, 2021). "In this case, it might be speculated that LETM1 upregulation can protect cancer cells from mitochondrial Ca2+ overload (whereas it might exacerbate such overload if the driving force changes, i.e., in depolarized mitochondria)." (PMID 34069047, 2021). "A comprehensive understanding of the mechanism by which LETM1 regulates mitochondrial Ca2+ handling, interactions with regulatory proteins such as CTMP and inter-organelle signaling is necessary to explore LETM1 as a potential reliable prognosticator and therapeutic target in cancer treatment." (PMID 33815143, 2021). "Leucine zipper/EF hand-containing transmembrane-1 (LETM1) is a mitochondrial inner membrane protein that is a potential biomarker of prognosis of several cancers, such as colorectal cancer, esophageal squamous cell carcinoma, breast cancer, lung non-small cell carcinoma, and gastric adenocarcinoma." (PMID 32163372, 2020). "In addition, the LETM1 expression is correlated with cancer stemness-related gene LGR5 (p < 0.001) and HIF1α expression (p < 0.001), but not with others." (PMID 31500591, 2019). "Despite the strong association between LETM1 expression and cancer, there have been no reports of LETM1 expression-based outcomes in tumor patients." (PMID 24689060, 2014). "Also, our current results in combination of detailed new information of the mechanism of AMPK action would provide us a good rationale to take LETM1 as a candidate for cancer therapy." (PMID 20824095, 2010). "LETM1 may also be involved in initiating resveratrol-induced cancer cell death." (PMID 33815143, 2021). "Furthermore, the expression levels of LETM1 markedly increased in various cancers compared with those in normal tissue, demonstrating that high LETM1 expression may be a potential tumor marker." (PMID 31500591, 2019). "Therefore, we tested whether hypoxic condition would promote LETM1 and cancer stemness gene LGR5 expression in NSCLC cells." (PMID 31500591, 2019). "Our study implied that the mitochondrial protein LETM1 may enhance ATP generation in cancer cells." (PMID 27556512, 2016). "Additionally, recent studies report that LETM1 may function in mitochondrial biogenesis, which is an important feature of human cancer." (PMID 24689060, 2014).
cancer (continued). "The effects of silencing LETM1 (Leucine zipper-EF-hand-containing transmembrane protein 1), a protein overexpressed in CRC tissues compared to normal tissues were studied and were found to suppress cancer stemness and proliferation." (PMID 35912261, 2022). "The correlation of LETM1 expression with Akt phosphorylation suggests that, in addition to LETM1-CHE/KHE activity, regulation of tumorigenesis by LETM1 may involve signaling through its constitutive binding partner CTMP in cancer cells." (PMID 33815143, 2021). "Conversely, protein levels of the better prognosis gene LETM1 showed an exactly opposite trend, since protein expression was identified as being lower (medium to absent) in 80% of cancer sections compared with normal tissue." (PMID 31083561, 2019). "Moreover, cancer stemness related genes such as CD44, CD133, LGR5, LSD1, OCT4, Sox2 and Sox9 were co-upregulated with LETM1 in A549 cells." (PMID 31500591, 2019). "Overall, our results suggest that the upregulation of LETM1 expression in NSCLC may play a key role in tumor growth and cancer cell proliferation, leading to poor prognosis." (PMID 31500591, 2019). "Beyond LETM1, the extent to which the mitochondrial acid/base transporters might contribute specifically to cancer development has, to our knowledge, not been directly studied." (PMID 34069047, 2021). "Moreover, the numbers of new capillary blood vessels around the cancer cells significantly higher in cases of LETM1-positive NSCLC compared to that in negative cases (p = 0.024) (ANOVA test)." (PMID 31500591, 2019). "However, LETM1's function in tumorigenesis and the regulation of its expression levels are largely unclear, and the role of LETM1 as a prognostic biomarker in cancer has not been reported to date." (PMID 24689060, 2014).
tumor (11 papers, 2010 to 2021). "This is further corroborated by the observation in prostate cancer cells, that the PI3K inhibitor LY294002, which stopped the migration and invasion of tumor cells, also caused the downregulation of LETM1." (PMID 33815143, 2021). "In conclusion, this is the first study to find that high expression of LETM1 is significantly associated with tumor size, portal vein emboli, metastasis, TNM stage, and overall survival time in HCC patients." (PMID 33552978, 2020). "In lung cancer, LETM1 overexpression promoted tumor formation by inhibiting 5'-adenosine monophosphate activated protein kinase (AMPK), a cellular bioenergetic sensor that activates autophagy at depleted ATP levels." (PMID 33815143, 2021). "Further analysis of the GEO database (tumours from 17 patients with CRC) using GSEA showed that positively regulated genes related to G2/M phase were enriched in the LETM1‐high expression group (NES = 1.5126858, FDR q‐value = 0.17041634)." (PMID 33314691, 2021). "Recent studies have shown that LETM1 also has important roles in tumorigenesis and tumour development." (PMID 33314691, 2021). "The findings of this study indicated that LETM1 is involved in HCC tumor cell aggressiveness by promoting cell proliferation and inhibiting autophagy and apoptosis." (PMID 33552978, 2020). "Tumor tissues were assessed by Western blotting, which revealed that the levels of Beclin1, LC3II/I, p-Bcl-2/Bcl-2, Bax, and caspase-3 were increased in sh-LETM1 tumor tissues compared with NC tumor tissues." (PMID 33552978, 2020). "The results revealed that both the relative mRNA level (p < 0.01) and the protein expression level (p < 0.01) of LETM1 in HCC tissues were significantly higher than those in adjacent tumor tissues." (PMID 33552978, 2020). "High LETM1 levels were found to be associated with better PFS in both II and III tumor stage GC patients." (PMID 31083561, 2019). "The comparison of mean RPKM (Reads Per Kilobase per Million mapped reads) between normal and tumor mRNAs indicated statistically significant increase of LETM1 expression in PTC." (PMID 27556512, 2016). "Based on these findings, up-regulation of LETM1 appears to play a critical role in altering mitochondrial metabolism and tumor behavior in PTC carcinogenesis through YAP1 transactivation." (PMID 27556512, 2016). "For the purpose, we analyzed the effect of LETM1 on tumor cell proliferation using proliferating cell nuclear antigen (PCNA) antibody." (PMID 20824095, 2010). "Changes in LETM1 expression also affect these processes, implicating it in the pathophysiology of several disease phenotypes, including metabolic, neurodegenerative, and neoplastic diseases." (PMID 33815143, 2021). "Moreover, the chi-square test and Pearson correlation analysis showed that LETM1 overexpression was significantly correlated with tumor size (p<0.001), portal vein emboli, metastasis (both p<0.01), and TNM stage of HCC (p<0.05)." (PMID 33552978, 2020). "Taken together, these results in this tumor formation experiment indicated that LETM1 may play an important role in the tumorigenicity of HCC cells." (PMID 33552978, 2020). "In contrast, the level of p62 was decreased in sh-LETM1 tumor tissues." (PMID 33552978, 2020). "In this study, we have demonstrated that LETM1 expression may be one of the independent prognostic factors, along with tumor stage and chemoradiotherapy." (PMID 24689060, 2014). "Univariate analysis demonstrated that tumor differentiation (P = 0.005), TNM stage (P = 0.002), chemoradiotherapy (P = 0.019), and LETM1 expression status were significantly associated with 5-year disease-free survival and overall survival in patients with HNSCC." (PMID 24689060, 2014). "Furthermore, the total tumor number was significantly decreased by adenoviral LETM1 delivery in the lungs." (PMID 20824095, 2010). "However, whether LETM1 would affect tumour cell metabolism through mitochondrial oxidative phosphorylation has not been investigated." (PMID 33314691, 2021).
tumor (continued). "Because ROS levels are regulated by multiple antioxidant enzymes, including Mn‐containing SOD2 in the mitochondrial matrix, we first analysed TCGA database by GEPIA and explored the correlations between LETM1 and SOD2 in CRC tumours." (PMID 33314691, 2021). "To demonstrate that RHPN1-AS1 promotes tumor progression in a LETM1-dependent manner, we transfected ES-2 and HEY cells stably overexpressing sh-RHPN1-AS1 with LETM1 overexpression vector." (PMID 32163372, 2020). "Then, the mRNA and protein levels of LETM1 in six HCC patient tissues and paired adjacent tumor tissues from the First Affiliated Hospital of Chongqing Medical University were determined by RT-qPCR and Western blotting." (PMID 33552978, 2020). "Immunohistochemical studies revealed that LETM1 was abundantly expressed in NSCLC tissues, and rarely expressed in adjacent non-tumor lung pulmonary alveoli, indicating that LETM1 potentially plays an important role in NSCLC development." (PMID 31500591, 2019). "We further found that restoration of LETM1 expression partially rescued the inhibition of tumor growth by RHPN1-AS1 silencing (data not shown)." (PMID 32163372, 2020). "LETM1 expression levels were not related to gender (P = 0.545), age (P = 0.466), primary site of tumor (P = 0.764), pT (P = 0.334), alcohol use history (P = 0.168), and smoking status of patients with HNSCC (P = 0.328)." (PMID 24689060, 2014). "For tumor stages, in 123 patients with advanced stage HNSCC, 96 (78.0%) had high levels of LETM1 expression, whereas, in the 53 patients with early stage HNSCC, only 19 (35.8%) showed high levels of LETM1 protein expression (P < 0.001)." (PMID 24689060, 2014).
infection (2 papers, 2022 to 2023). The state of being infected such as from the introduction of a foreign agent such as serum, vaccine, antigenic substance or organism. "H460 cells were transiently transfected with Red-Mito for 24 h, followed by co-infection with Ad-GFP-LC3B and Ad-LacZ or Ad-LETM1 for 24 h (first panel and third panel, respectively)." (PMID 35680871, 2022).
cardiac diseases (1 paper, 2025). "While its role has been extensively studied in other systems such as neuronal and cancer cells the impact of Letm1 dysregulation on cardiomyocyte function and its contribution to cardiac diseases remain largely unexplored." (PMID 40849623, 2025).
cardiovascular disease (1 paper, 2025). "Nonetheless, our results provide compelling evidence that Letm1 plays a central role in modulating mitochondrial homeostasis and cardiac remodeling, forming a foundation for deeper exploration of its potential as a therapeutic target in cardiovascular disease." (PMID 40849623, 2025).
mitochondrial disease (1 paper, 2022). "Here, we describe 18 affected individuals from 11 unrelated families presenting with clinical features suggestive of a mitochondrial disease largely involving the CNS in which exome sequencing (ES) identified novel and ultra-rare bi-allelic segregating LETM1 variants." (PMID 36055214, 2022).
LETM1 also shares sentences with these, for which no sentence is quoted: psychosis (2 papers); adenoma (1); cerebellar ataxia (1); Cerebellar atrophy (1); colorectal adenocarcinoma (1); convulsion (1); esophageal squamous cell carcinoma (1); fibrosis (1); gastric adenocarcinoma (1); glioblastoma (1); growth deficiency (1); lactic acidosis (1); Neurodevelopmental delay (1); neuropathy (1); osteosarcoma (1); Parkinson disease (1); prostate carcinoma (1); Respiratory insufficiency (1); retinal degeneration (1); triple-negative breast carcinoma (1).